C5AR1 (complement C5a receptor 1)
Description:
Receptor for the chemotactic and inflammatory peptide anaphylatoxin C5a, stimulating chemotaxis, granule enzyme release, intracellular calcium release and superoxide anion production. Ligand binding causes a conformation change that triggers signaling via guanine nucleotide-binding proteins (G proteins) and modulates the activity of downstream effectors, such as adenylate cyclase. C5AR1 is coupled to G(i)/G(o) (GNAI1 or GNAO1) G alpha proteins and mediates inhibition of adenylate cyclase. The ligand interacts with at least two sites on the receptor: a high-affinity site on the extracellular N-terminus, and a second site in the transmembrane region which activates downstream signaling events.
Synonyms: C5aR; CD88; C5R1; C5A
Tractability: Small molecule: an approved drug acts on it; a structure with a bound ligand is known; a high-quality ligand is known; it belongs to a druggable protein family. Antibody: a drug acting on it is in phase 2 or 3 trials; UniProt places it where antibodies can reach, with high confidence; its Gene Ontology location is reachable by antibodies, with high confidence; UniProt predicts a signal peptide or a membrane-spanning region. PROTAC: its protein half-life has been measured; a small molecule that binds it is known.
Target class: Family A G protein-coupled receptor; Anaphylatoxin receptor family; Membrane receptor; Anaphylatoxin receptor; Peptide receptor (family A GPCR)
Chemical probes: Hoo-Phe-Orn-Pro-hle-Pff-Phe-NH2, avacopan (high quality)
Gene: Protein-coding gene on chromosome 19 (47,290,023 to 47,322,066, forward strand). Ensembl gene ENSG00000197405.
Subcellular location: Cell membrane; Cytoplasmic vesicle
Subcellular location (Human Protein Atlas): Golgi apparatus; Vesicles
Pathways (Reactome):
Immune System: Neutrophil degranulation; Regulation of Complement cascade
Signal Transduction: G alpha (i) signalling events; Peptide ligand-binding receptors
Gene Ontology:
Molecular function: complement component C5a receptor activity; G protein-coupled receptor activity; protein binding; complement receptor activity
Biological process: adenylate cyclase-inhibiting G protein-coupled receptor signaling pathway; complement component C5a signaling pathway; complement receptor mediated signaling pathway; mRNA transcription by RNA polymerase II; positive regulation of epithelial cell proliferation; positive regulation of ERK1 and ERK2 cascade; amyloid-beta clearance; astrocyte activation; cellular defense response; chemotaxis; cognition; immune response; inflammatory response; microglial cell activation; phospholipase C-activating G protein-coupled receptor signaling pathway; positive regulation of cytosolic calcium ion concentration; presynapse organization; sensory perception of chemical stimulus; signal transduction; G protein-coupled receptor signaling pathway; positive regulation of angiogenesis; positive regulation of macrophage chemotaxis; positive regulation of neutrophil chemotaxis; positive regulation of vascular endothelial growth factor production; regulation of immune system process
Cellular component: apical part of cell; basolateral plasma membrane; cytoplasmic vesicle; plasma membrane; secretory granule membrane; membrane
Genetic constraint (gnomAD): Loss-of-function variants: 0 observed, 0.78 expected, observed/expected ratio (o/e) 0, 90% interval 0 to 1.78. That is too few expected variants to judge how well the gene tolerates losing a copy. Missense variants: 418 observed, 478.35 expected, observed/expected ratio (o/e) 0.87, 90% interval 0.81 to 0.95. Synonymous variants: 209 observed, 217.72 expected, observed/expected ratio (o/e) 0.96, 90% interval 0.86 to 1.08.
Homologues: Orthologues: chimpanzee C5AR1 (98% identical), macaque C5AR1 (90% identical), rabbit C5AR1 (75% identical), pig C5AR1 (70% identical), dog C5AR1 (69% identical), guinea pig C5AR1 (66% identical), mouse C5ar1 (66% identical), tropical clawed frog c5ar1 (40% identical), zebrafish c5ar1 (36% identical). Paralogues in human: C5AR2 (35% identical), C3AR1 (35% identical), CMKLR1 (33% identical), FPR2 (31% identical), FPR3 (30% identical), FPR1 (29% identical), GPR33 (25% identical), GPR32 (24% identical).
Diseases named in the same sentence as C5AR1 in open-access papers:
C5AR1 is named in the same sentence as 295 diseases in open-access papers, as found by Europe PMC text mining. Sharing a sentence is not in itself a finding about the gene and the disease. The quoted sentences say what the papers report.
Sepsis (95 papers, 2008 to 2025). Sepsis is defined as life-threatening organ dysfunction caused by a dysregulated host response to infection. "Animal studies employing C5aR1—deficient mice have shown notably enhanced survival rates in mild—to—moderate sepsis models." (PMID 40877572, 2025). "Transcriptomic analysis revealed significant upregulation of C5aR1 in brain tissue associated with sepsis-induced WMI." (PMID 41584453, 2025). "In experimental models of meningococcal infection, C5aR1-deficient mice display increased resistance to sepsis, whereas C5aR1 activation exacerbates disease progression." (PMID 41584453, 2025). "Meanwhile, in mouse models of cecal ligation and puncture-induced sepsis, either C5aR1 or C5aR2 deficiency was protective, reflected in improved survival outcomes or better cardiac functions." (PMID 39021433, 2024). "In humans, enhanced C3a, C5a, and sC5b-9 concentrations in the blood and corresponding loss of the C5aR1 and C5aR2 have been proposed as driver for sepsis-induced complications and multiple organ failure." (PMID 34191093, 2021). "C5aR1 dysfunction negatively influences cellular effector functions and is associated with poor clinical outcome in sepsis patients." (PMID 32983087, 2020). "Cytokine release through excessive C5aR1 signalling on pro‐inflammatory macrophages and other leucocytes is thought to contribute to the cytokine storm associated with sepsis and MOF." (PMID 32559343, 2020). "Especially, dysfunction of C5aR1 has been implicated in various pathological conditions such as sepsis, autoimmunity and inflammation." (PMID 32983087, 2020). "When C5a activates C5aR1, the C5a/C5aR1 complex is rapidly internalized, thereby reducing surface C5aR1 levels on neutrophils; this phenomenon has been linked to poor outcome in sepsis patients as well as in rodent models of sepsis." (PMID 29362231, 2018). "In contrast, the results of our study, focusing on sepsis caused by N. meningitidis, therefore represent an outstanding example of successful interference with the C5a/C5aR1 axis even after onset of the disease." (PMID 29362231, 2018). "In sepsis, excessive complement activation and C5a generation in animal models and in humans with sepsis was associated with reduced C5aR1 expression." (PMID 29121655, 2017). "In cardiomyocyts (CMs) from CLP-septic C5aR1 and C5aR2 KO mice, both receptors contributed to the cytokine storm that have been linked to cardiosuppression in sepsis, demonstrated by reduced levels of IL-6, TNFα, IL-1β, IL-10, and others." (PMID 28706957, 2017). "An association between sepsis and C5aR1 expression has also been shown for NK cells." (PMID 37373467, 2023). "Interestingly, in burn injury and after cecal ligation and puncture (CLP) sepsis, C5aR1 was also upregulated in heart tissue, which is associated with depressed cardiac function." (PMID 33450984, 2021). "An increased intrapulmonary or intra alveolar C5a level during sepsis may cause severe ALI via binding to the C5aR1 or C5aR, which induces an increased neutrophil infiltration into the septic lung and cytokine/chemokine storm." (PMID 32849610, 2020). "In contrast to C5ar1−/- and C5ar2−/- mice, C3aR−/- mice were more susceptible to Nme sepsis." (PMID 31274379, 2019). "The detrimental effects of C5aR1 during sepsis have been linked to neutrophil dysfunction." (PMID 31274379, 2019). "In a rat model of a CLP-induced sepsis, the loss of C5aR1 is associated with a poor prognosis." (PMID 26176669, 2015). "Most importantly, we could demonstrate that interference with complement-derived inflammation caused by pharmacological blockade of C5aR1 ameliorates inflammatory cytokine release in human whole-blood infection and leads to increased survival in experimental N. meningitidis sepsis." (PMID 29362231, 2018).
Sepsis (continued). "Since C5ar1 deficiency ameliorated the course of experimental N. meningitidis sepsis and its blockade also lowered the proinflammatory cytokine/chemokine levels in a human whole-blood infection model, we speculated that C5aR1 might therefore represent a potential target for treatment." (PMID 29362231, 2018). "Mice in the sepsis group had significantly higher levels of C5aR1 in their brain tissues, according to IHC analysis." (PMID 41584453, 2025). "Mice with polymicrobial sepsis exhibited significant upregulation of C5ar1 gene expression after 8 and 24 h, respectively." (PMID 40253667, 2025). "The expression of C5aR1 in intestinal mucosal epithelial cells of mice in the sepsis group was significantly upregulated." (PMID 41584453, 2025). "In summary, glycine appears to exert multifaceted protective effects in sepsis by specifically targeting the C5aR1-mediated complement activation pathway in both the central nervous system and the gut." (PMID 41584453, 2025). "Fourthly, the transcriptomic analysis revealed that C5aR1 is a key mediator of septicemia-related brain injury, and its expression can be regulated through glycine intervention." (PMID 41584453, 2025). "This highlights the C5a–C5aR1 axis as a key mediator in diseases like sepsis and rheumatoid arthritis." (PMID 41550949, 2025). "Here, we confirmed the local increase of C5ar1 expression in cardiomyocytes during sepsis as previously demonstrated, and showed a tendential downregulating effect of BMMSC administration." (PMID 40253667, 2025). "Glycine intervention significantly decreased C5aR1 immunoreactivity, resulting in a smaller positively stained region compared to the sepsis group (P < 0.05)." (PMID 41584453, 2025). "Western blot analysis revealed that the C5aR1 protein expression in ileum tissue increased significantly in the sepsis group and placebo group (P < 0.01), while in mice with glycine treatment, it decreased significantly (P < 0.05)." (PMID 41584453, 2025). "This study investigated the relationship between C5ar1 and NET levels in neutrophils from sepsis rat by silencing C5ar1 in CLP rats and demonstrated the effect of silenced-C5ar1 to reduce NET levels." (PMID 38165570, 2024). "In a model of sepsis, however, only targeting both C5aR1 and C5aR2 with the C5a mutant peptide A8Δ71–73 improved mouse survival." (PMID 38458648, 2024). "C5ar1 mice are more resistant to invasive meningococcal infection than wild-type mice, however, it is interesting that the pharmacological blockade of C5ar1 improves the survival rate of mice after sepsis induction." (PMID 38165570, 2024). "During sepsis, expression of C5ar1 is up regulated in organs, including the lung, liver, heart, and kidney." (PMID 39178306, 2024). "Both C5a receptors (C5aR1 and C5aR2) are known to be required for histone appearance in plasma during polymicrobial sepsis." (PMID 39201339, 2024). "Anaphylatoxin C5a and its receptors C5aR1 and -2 are known to be involved in sepsis pathogenesis, with C5aR1 mainly exerting pro-inflammatory effects." (PMID 37373467, 2023). "For outcome-related differences in C5aR1 expression, i.e., late-onset sepsis patients vs. unaffected controls, larger cohort studies are required." (PMID 37373467, 2023). "The reduced expression of C5aR1 on blood neutrophils correlates inversely with the severity of sepsis, mortality rate and outcome." (PMID 37373467, 2023). "In fact, inhibition of C5aR1 signaling reduced the consequences of exacerbated bacterial infection such as is observed in sepsis." (PMID 37104043, 2023). "No direct association between the inflammatory context of preterm birth or early-onset sepsis with C5aR1 patterns in neutrophils was found." (PMID 37373467, 2023). "Findings of a hyporesponsive status of NK cells during sepsis support this theory of C5aR1-mediated immunoparalysis." (PMID 37373467, 2023).
Sepsis (continued). "As the experimental blockade of C5a and C5aR1 has been shown to result in an improved sepsis outcome, therapeutic targets of the complement system in human sepsis therapy are the focus of current research and seem to be a promising approach." (PMID 37373467, 2023). "The C5aR1 sits in a central hub of the complement inflammation cascade by directly binding C5a to induce inflammation in sepsis." (PMID 35447887, 2022). "Our studies of polymicrobial sepsis have highlighted the role of complement activation products (especially C5a anaphylatoxin and its receptors C5aR1 and C5aR2) in adverse effects of sepsis." (PMID 33425963, 2020). "Our studies indicate that appearance of extracellular histones in sepsis is complement and C5aR1-dependent." (PMID 33425963, 2020). "KO of C5aR1 substantially reduces the harmful effects of sepsis in mice, reducing multiorgan injury and greatly improving survival after CLP." (PMID 33425963, 2020). "The blockade of C5AR1 with polyclonal anti-C5AR1 antibodies was protective and increased survival in an animal sepsis model." (PMID 32471891, 2020). "Here, we aimed to extend our analyses to the relative contributions of all three anaphylatoxin receptors, C3aR, C5aR1 and C5aR2 to meningococcal nasopharyngeal colonization as well as sepsis pathology using in vivo and ex vivo models of disease." (PMID 31274379, 2019). "Considering the small differences between sepsis outcome after blockade of C5aR1 alone (PMX205) versus C5aR1 plus C5aR2 (A8Δ71−73), the additional effect of blocking C5aR2 seems to be minor." (PMID 31274379, 2019). "We recently discovered that C5aR1 exacerbates the course of the disease, revealing a downside of complement in Nme sepsis." (PMID 31274379, 2019). "In CLP-driven sepsis, for example, only the combined inhibition of C5aR1 and C5aR2 improves animal survival." (PMID 29520270, 2018). "Next, we assessed the specific contribution of C5aR1 during N. meningitidis sepsis by comparing the outcomes seen with systematic infections of WT and C5ar1−/− mice." (PMID 29362231, 2018). "Numerous studies showed a benefit of prophylactic blockade of C5a or C5aR1 prior to induction of an inflammatory insult in experimental inflammatory bowel disease, asthma, or sepsis (64, –, 67)." (PMID 29362231, 2018). "In clinical sepsis, an enhanced presence of the complement C5a receptor C5aR1 on MVs in patients with septic shock has been demonstrated, suggesting an important role in the outcome." (PMID 29696020, 2018). "Yet our study is the first in the context of N. meningitidis sepsis to demonstrate the devastating effect of the inflammatory branch of complement, which is mediated by complement split fragment C5a and its receptor C5aR1." (PMID 29362231, 2018). "We found that C5aR1 activation exaggerates the detrimental cytokine response to N. meningitidis sepsis." (PMID 29362231, 2018). "In support of this, a further study identified a 20-fold higher gene expression of C5aR1 in blood leukocytes of 26 patients with severe sepsis compared to healthy volunteers." (PMID 29696020, 2018). "Enticingly, pharmacologic C5aR1 blockade enhanced mouse survival and lowered meningococcal burden even when the treatment was administered after sepsis induction." (PMID 29362231, 2018). "WT mice showed an aggravated course of N. meningitidis sepsis, including a higher bacterial burden and also higher levels of inflammatory mediators in the blood than were seen with C5ar1−/− mice." (PMID 29362231, 2018). "In a cohort of sepsis patients, neutrophils exhibit decreased C5aR1 expression, but enhanced numbers of circulating C5aR1 (C5aR1 on MVs), resulting in an impairment of neutrophil function." (PMID 29696020, 2018). "Interaction of C5a with the C5a receptor 1 (C5aR1) can induce dramatic contractile dysfunction in cardiomyocytes in vitro and in vivo during sepsis." (PMID 29121655, 2017).
Sepsis (continued). "However, research on blood neutrophils in experimental and clinical sepsis showed that the downregulation of C5aR2 levels in PMNs demonstrated by western blot and flow cytometry was associated with a poor prognosis, indicating the protective role of C5aR2 in counterbalancing C5aR1." (PMID 28706957, 2017). "This is in contrast to earlier studies in rats, which showed increased C5aR1 expression in the heart 24 h after burn injury and on cardiomyocytes obtained from models of experimental sepsis." (PMID 29121655, 2017). "In experimental CLP-sepsis complement C5a receptor 1 knock out (C5aR1-/-) and C5a receptor 2 knock out (C5aR2-/-) mice had superior survival rates compared to wt." (PMID 27437704, 2016). "Given the importance of C5a-C5aR1 interactions in promoting the onset and development of sepsis, we sought to investigate the regulation of IL-1β production by C5aR1 signaling in a TLR4-mediated, mouse endotoxemia model." (PMID 27382187, 2016). "This is in agreement with previous studies that have described a critical role for C5aR1 engagement in exacerbating sepsis immunopathology." (PMID 27382187, 2016). "Notably, C5aR1 is markedly expressed in both the ileum and the brain, suggesting a potential role in mediating gut-brain crosstalk during sepsis." (PMID 41584453, 2025). "The top ten differentially expressed genes in this study include Gm29879, Lcn2, Cxcl10, Zbp1, Lbhd2, C5aR1, Cxcl10, Lbhd2, Cxcl9, and Fpr1, all of which might play a role in the pathophysiology of sepsis-induced WMI." (PMID 41584453, 2025). "Similarly, a C5ar1 antagonist increased survival in CLP-induced sepsis and reduced bacterial counts in several organs." (PMID 39178306, 2024). "Additionally, the C5ar1 gene was significantly upregulated with interesting potential in sepsis and used for further study." (PMID 38165570, 2024). "Silencing C5aR1 increased survival of CLP mice in sepsis and decreased the secretion of cytokines." (PMID 38165570, 2024). "Additionally, silenced C5ar1 inhibited the TLR2, TLR4, and peptidylarginine deiminase 4 expression levels, which suggested the improvement of silenced C5ar1 on sepsis via inhibiting NETs and the TLR signaling pathway." (PMID 38165570, 2024). "A downregulation of C5aR1 on neutrophils during sepsis inversely correlated with sepsis severity." (PMID 37373467, 2023). "When we compared the C5aR1 3′UTR from the sepsis studies and the in vitro model; we observed an increase in transcription when comparing healthy control raw reads versus septic shock and when comparing raw reads from the whole blood model activated with bacteria versus healthy control." (PMID 35447887, 2022). "Furthermore, during the inflammatory condition of CLP sepsis, C5a-C5aR1 interactions were shown to induce an excessive amount of cytosolic ROS and Ca2+i in CMs." (PMID 33450984, 2021). "Some sepsis-relevant microbial toxins are exemplarily summarized: Panton-Valentine leukocidin (PVL) is a toxin produced by some staphylococcal strains which can interact with the C5aR1 and induce lytic pores in neutrophils as well as NETosis." (PMID 33567720, 2021). "C5aR1 is a G-protein coupled receptor highly expressed on neutrophil granulocytes and its activation aggravates chronic and acute inflammatory conditions, such as sepsis, ischemia-reperfusion injury, inflammatory bowel disease and others." (PMID 31274379, 2019). "Thus, we expanded upon our recent observation that C5aR1 aggravates Nme sepsis pathophysiology in showing that C3aR is protective, whereas C5aR2, like C5aR1, is detrimental in the mouse Nme sepsis model." (PMID 31274379, 2019). "For example, C5aR1 activation is pivotal for efficient pathogen removal in cases of Pseudomonas aeruginosa lung infection, while C5aR1 fuels systemic hyperinflammation in polymicrobial sepsis after cecum ligation and puncture (CLP) and is detrimental to the host." (PMID 29362231, 2018).